MIR205HG (MIR205 host gene)
Synonyms: LEADR; miPEP205; LINC00510; NPC-A-5
Gene: Long non-coding RNA gene on chromosome 1 (209,427,531 to 209,432,855, forward strand). Ensembl gene ENSG00000230937.
Gene Ontology:
Biological process: miRNA-mediated post-transcriptional gene silencing
Cellular component: RISC complex
Diseases named in the same sentence as MIR205HG in open-access papers:
MIR205HG is named in the same sentence as 23 diseases in open-access papers, as found by Europe PMC text mining. Sharing a sentence is not in itself a finding about the gene and the disease. The quoted sentences say what the papers report.
cervical carcinoma (9 papers, 2019 to 2025). A carcinoma arising from either the exocervical squamous epithelium or the endocervical glandular epithelium. "MIR205HG was upregulated in cervical cancer tissues and cell lines, and its depletion inhibited the proliferation and metastasis of cervical cancer cells." (PMID 35525925, 2022). "A previous study reported that MIR205HG inhibits progression of cervical cancer by interacting with SRSF1 and modulating KRT17 expression." (PMID 33535182, 2021). "MicroRNA-205 host gene (MIR205HG) has been found as a oncogene in cervical cancer by modulating miR-122-5p/FOXP2 axis." (PMID 31649871, 2019). "Likewise, MIR205HG also exerts oncogenic effects in cervical cancer, esophageal squamous cell carcinoma, and osteosarcoma." (PMID 38252669, 2024). "Likewise, studies have shown that MIR205HG functioned as an oncogene in esophageal cancer, cervical cancer and head & neck squamous cell carcinoma by interacting with miR-214, SRSF1 and miR-590-3p, respectively." (PMID 33949284, 2021). "The results of GEPIA database showed that CDKN2B-AS1, MIR205HG, and HAGLROS were highly expressed in cervical cancer, and patients with high expression levels had poorer prognoses." (PMID 40822023, 2025). "The prognostic significance of CDKN2B-AS1, MIR205HG, HAGLROS, GATA6-AS1, and DICER1-AS1 in cervical cancer patients was evaluated by using the KM-Plotter database." (PMID 40822023, 2025). "The results showed that CDKN2B-AS1, MIR205HG, and HAGLROS were highly expressed in cervical cancer, whereas GATA6-AS1 and DICER1-AS1 showed low expression levels in cervical cancer." (PMID 40822023, 2025). "LEADR/MIR205HG expression also responded to p63 modulation in both prostate basal and cervical carcinoma cells, suggesting direct regulation." (PMID 30659180, 2019). "Furthermore, MIR205HG could also target SRSF1 and modulate KRT17 to mediate biological activities of cervical cancer cells." (PMID 34926294, 2021).
melanoma (7 papers, 2019 to 2025). A malignant, usually aggressive tumor composed of atypical, neoplastic melanocytes. "ALKBH5 expression levels were augmented in melanoma cells, and MIR205HG downregulation decreased the mRNA levels of ALKBH5 while JMJD2C overexpression promoted the mRNA levels of ALKBH5 (P < 0.01)." (PMID 38252669, 2024). "Collectively, our findings initially demonstrated that MIR205HG played an oncogenic role in melanoma through HuR-mediated stabilization of JMJD2C." (PMID 38252669, 2024). "The expression pattern of MIR205HG was determined in cultured cell lines and the results showed the upregulation of MIR205HG expression in melanoma cells (P < 0.01)." (PMID 38252669, 2024). "A375 cells with higher MIR205HG expression and A2058 cells with lower MIR205HG expression were selected to investigate the impact of MIR205HG on melanoma cell proliferation." (PMID 38252669, 2024). "Our results showed that MIR205HG downregulation inhibited invasion and migration of melanoma cells (P < 0.01)." (PMID 38252669, 2024). "The objective of our study was to investigate the molecular mechanism by which MIR205HG regulates melanoma cell growth and provide a novel theoretical reference for melanoma treatment." (PMID 38252669, 2024). "Generally, MIR205HG facilitated proliferation, invasion, and migration of melanoma cells through HuR-mediated stabilization of JMJD2C and increasing ALKBH5 transcription by erasing H3K9me3." (PMID 38252669, 2024). "In this study, MIR205HG expression was found to be higher in melanoma cell lines and MIR205HG downregulation inhibited proliferation, invasion, and migration of melanoma cells." (PMID 38252669, 2024). "Overall, our findings initially disclosed that MIR205HG downregulation retarded melanoma cell proliferation, invasion, migration, and in vivo tumor growth by repressing the JMJD2C/ALKBH5 axis." (PMID 38252669, 2024). "Most importantly, MIR205HG knockdown has been previously demonstrated to inhibit proliferation, invasion, and migration of melanoma cells, as well as tumor growth in vivo." (PMID 38252669, 2024). "The expression levels of JMJD2C were markedly increased in melanoma cells but were downregulated in response to MIR205HG downregulation (P < 0.05)." (PMID 38252669, 2024). "Taken together, these results demonstrate that MIR205HG silencing or miR-299-3p agomir significantly inhibits the in vivo growth of melanoma." (PMID 33535182, 2021). "In summary, our study demonstrates that silencing MIR205HG suppresses melanoma growth and progression by inhibiting the VEGFA expression and EMT via miR-299-3p." (PMID 33535182, 2021). "Taken together, our data demonstrates that MIR205HG knockdown inhibits melanoma growth and progression by suppressing VEGFA expression and EMT via miR-299-3p." (PMID 33535182, 2021). "Taken together, these results demonstrate that knockdown of MIR205HG significantly suppressed proliferation of melanoma cells." (PMID 33535182, 2021). "Taken together, these data demonstrate that MIR205HG silencing inhibits migration and invasion of melanoma cells via miR-299-3p." (PMID 33535182, 2021). "Our data is consistent with this finding and suggests that MIR205HG is a potential prognostic biomarker in melanoma." (PMID 33535182, 2021). "Next, we explored the mechanism by which MIR205HG regulated in vitro and in vivo melanoma growth and progression." (PMID 33535182, 2021). "We also demonstrated that MIR205HG silencing inhibited the in vitro migration and invasion of melanoma cells." (PMID 33535182, 2021). "In agreement with our results, MIR205HG has been demonstrated to accelerate the proliferation of melanoma cells by inducing the canonical oncogenic Wnt/β-catenin signaling pathway and support melanoma tumor growth by mediating the miR-299-3p/vascular endothelial growth factor A axis." (PMID 38252669, 2024). "Finally, we analyzed the role of MIR205HG in melanoma by generating the xenograft melanoma model mice." (PMID 33535182, 2021).
melanoma (continued). "Among them, MIR205HG expression is associated with the poor outcome of patient and its expression is positively correlated with the expressions of immune checkpoints like PD-1, CTLA4, LAG3, and TIM3 in adenocarcinoma and melanoma." (PMID 35096622, 2021). "This makes MIR205HG a potential therapeutic target for the treatment of melanoma." (PMID 33535182, 2021). "This suggested that MIR205HG silencing increased apoptosis of melanoma cells via miR-299-3p." (PMID 33535182, 2021). "Our results showed that MIR205HG might be a potential therapeutic target or candidate prognostic biomarker in melanoma." (PMID 31649871, 2019). "However, it remains poorly understand how MIR205HG regulates melanoma cell growth." (PMID 38252669, 2024). "Thus, MIR205HG is a potential therapeutic target for melanoma." (PMID 33535182, 2021). "However, it is unclear whether MIR205HG regulates the JMJD2C/ALKBH5 axis to function in melanoma." (PMID 38252669, 2024). "JMJD2C was found to be higher in melanoma cell lines, and MIR205HG downregulation reduced the expressive level and mRNA stability of JMJD2C, while HuR upregulation played an opposite role, indicating that MIR205HG bound to HuR and stabilized expression." (PMID 38252669, 2024). "Thus, MIR205HG, JMJD2C, and ALKBH5 may be candidate therapeutic targets for melanoma treatment." (PMID 38252669, 2024). "However, the biological function of MIR205HG in melanoma has not been fully investigated." (PMID 33535182, 2021).
lung squamous cell carcinoma (6 papers, 2019 to 2024). "MIR205HG acts as a competing endogenous RNA to expedite cell proliferation and progression via targeting miR-299-3p in lung squamous cell carcinoma." (PMID 35525925, 2022). "Additionally, the gene MIR205HG, a pivotal focus in our study, exhibits variations across various cancer types and even within lung squamous cell carcinoma." (PMID 38612418, 2024). "TCGA data show LEADR/MIR205HG upregulation in tumors with basal phenotype (e.g., cervical and lung squamous cell cancers) and downregulation in breast and prostate adenocarcinomas compared to their normal counterparts, thus mirroring miR-205 modulations." (PMID 30659180, 2019).
esophageal squamous cell carcinoma (2 papers, 2023 to 2024). Esophageal squamous cell carcinoma (ESCC) is a type of esophageal carcinoma (EC) that can affect any part of the esophagus, but is usually located in the upper or middle third. "In addition, MIR205HG promotes esophageal squamous cell carcinoma progression." (PMID 37189408, 2023).
bladder cancer (1 paper, 2025). "Altogether, MIR205HG/LEADR gene is one of the top ncRNAs downregulated during bladder cancer progression." (PMID 40461454, 2025). "To understand the transcriptional regulation of LEADR, we ranked all known human transcription factors based on their co-expression with MIR205HG in TCGA bladder cancer cohort and identified p63 as the top hit." (PMID 40461454, 2025). "Indeed, MIR205HG expression was strongly correlated with TP63 both in bladder cancer and across all TCGA cancer types." (PMID 40461454, 2025).
colon cancer (1 paper, 2018). "We noted that 11 lncRNAs, SCARNA10, RPPH1, LINC01419, ERVH48-1, RMRP,CH507-513H4.3, MIR205HG, CH507-513H4.6, LINC00400, RP11-774D14.1 and AC006050.2, were also differentially expressed in colon cancer samples compared with the normal samples." (PMID 29420609, 2018).
pulmonary fibrosis (1 paper, 2025). Chronic progressive interstitial lung disorder characterized by the replacement of the lung tissue by connective tissue, leading to progressive dyspnea, respiratory failure, or right heart failure. "We investigated whether Mir205hg is upregulated in bleomycin treatment, a commonly used model of pulmonary fibrosis." (PMID 40059822, 2025).
squamous cell carcinoma (1 paper, 2024). A carcinoma arising from squamous epithelial cells. "By validating the expression profiles of six specific genes (MIR205HG, KRT5, KRT6A, KRT6C, SERPINB5, and DSG3), selected based on a previously established 53-gene signature, we consistently observed higher expression levels in squamous cell carcinoma (SCC) compared to adenocarcinoma (ADC)." (PMID 38612418, 2024).
tumor (13 papers, 2019 to 2025). "MIR205HG modulates the tumor microenvironment by immune cell infiltration and cytokine expression, suppressing the oncogenic pathway." (PMID 40558258, 2025). "High expression of MIR205HG has been widely observed in HB tissues and cell lines, providing evidence for its potential as a tumor marker and therapeutic target." (PMID 41393242, 2025). "Of note, LEADR was localised within nuclei of tumour cells as assessed by fluorescence in situ hybridization (FISH) using MIR205HG or control ACTB (β-actin) probes, whereas the nuclei of T24 and TCCSUP cells were negative for MIR205HG." (PMID 40461454, 2025). "Our results revealed that MIR205HG downregulation inhibited tumor growth and reduced the positive rate of Ki67 in tumor tissues (P < 0.01)." (PMID 38252669, 2024). "Thereafter, we established the xenograft mouse model and found that MIR205HG downregulation suppressed tumor growth and reduced the positive rate of Ki67, together with reductions in JMJD2C and ALKBH5 levels in tumors." (PMID 38252669, 2024). "First, MIR205HG was found to be significantly overexpressed in HB tissues and cell lines, suggesting that it may act as a tumor promoter." (PMID 41393242, 2025). "Finally, their findings declared that MIR205HG functions as a tumor suppressor in the development of BE and EAC, at least in part through its effect on the Hedgehog signaling pathway." (PMID 35525925, 2022). "This demonstrates contrasting roles for MIR205HG in different tumor types." (PMID 33535182, 2021). "In both TCGA and GSE21034 cohorts, LEADR/MIR205HG expression alone was able to discriminate tumor vs. normal samples, suggesting that LEADR/MIR205HG loss may be an inescapable early event in prostate carcinogenesis." (PMID 30659180, 2019). "Recent studies have shown that the lncRNA MIR205HG activates the PI3K/AKT signaling pathway by competitively binding to miR-205–5p, thereby promoting tumor progression." (PMID 41393242, 2025). "In our study,the expressions of CHRM3.AS2, MIR205HG, and LINC00661 were significantly increased in tumor tissues of CCA patients, further verifying the prognostic prediction value of the established signatures for CCA." (PMID 34926294, 2021). "The expressions of CHRM3.AS2, MIR205HG, and LINC00661 from the TCGA and GEO databases were remarkably upregulated in tumor tissues compared with those in normal tissues." (PMID 34926294, 2021). "The box plot showed that MIR205HG was expressed at higher levels in tumor tissues than in normal adjacent tissues." (PMID 40302796, 2025). "To reveal the intra-tumor heterogeneity of malignant epithelial cells, we categorized the obtained cells into four subtypes: C0 TRPM4+ malignant cells, C1 SLPI+ malignant cells, C2 MIR205HG+ malignant cells, and C3 NEFH+ malignant cells." (PMID 39759507, 2024). "Reduction of LEADR/MIR205HG expression in PRAD was confirmed in one of the largest available microarray datasets (GSE21034), where its levels tend to decrease progressively as the tumor acquires a more undifferentiated or metastatic phenotype." (PMID 30659180, 2019).
cancer (10 papers, 2021 to 2025). A tumor composed of atypical neoplastic, often pleomorphic cells that invade other tissues. "It is implicated that MIR205HG widely participates in diverse types of cancers." (PMID 34996511, 2022). "Inhibition of MIR205HG expression reduces cancer cell growth, migration, and epithelial-mesenchymal transition processes and promotes cancer cell apoptosis." (PMID 36544782, 2022). "An oncogenic role has been proposed for MIR205HG in several cancers characterized by the expansion of basal cells, such as cervical, lung squamous cell, head and neck squamous cell carcinomas." (PMID 35784469, 2022). "Research shows that MIR205HG functions as a fundamental player in various human cancer by affecting different pathways in a context-dependent manner." (PMID 33949284, 2021). "Further study is needed to explore the expression, clinical implication and biological function of MIR205HG in other malignant tumors." (PMID 33949284, 2021). "LncRNAs such as CDKN2B-AS1, MIR205HG, HAGLROS, GATA6-AS1 and DICER1-AS1 are related to cancer research." (PMID 40822023, 2025). "MIR205HG expression levels could help predict prognosis in PTC; modulating MIR205HG expression may be a potential strategy for cancer treatment." (PMID 40558258, 2025). "MIR205HG, PIWIL1, and SLC16A9 are the only genes that were upregulated in cancer samples across all racial groups, but they do not impact survival." (PMID 40558258, 2025).
MIR205HG also shares sentences with these, for which no sentence is quoted: osteosarcoma (3 papers); adenocarcinoma (2); prostate carcinoma (2); Ataxia (1); basal cell carcinoma (1); breast carcinoma (1); esophageal adenocarcinoma (1); esophageal cancer (1); gastric cancer (1); head & neck squamous cell carcinoma (1); hepatoblastoma (1); lymph node (1); prostate adenocarcinoma (1).